TNF (tumor necrosis factor)
Diseases named in the same sentence as TNF in open-access papers (continued):
Sharing a sentence is not in itself a finding about the gene and the disease.
ovarian carcinoma (continued). "In ovarian cancer, Paclitaxel’s interaction with TLR4 on TAMs activates NF-κB, shifting macrophages toward an M1 profile marked by increased production of pro-inflammatory cytokines such as TNFα and IL12." (PMID 40330466, 2025). "TNFα and IFNγ enhance MUC16 expression in breast, endometrial, and ovarian cancer cells through the NFκB pathway, with this upregulation linked to immune regulatory factor activity, indicating that MUC16 modulation may benefit treatment." (PMID 38361923, 2024). "In microglia and ovarian cancer cells, RGS10 regulates inflammatory signaling by a G protein-independent mechanism, linking RGS10 to the inflammatory signaling mediators tumor necrosis factor-alpha (TNFα) and cyclooxygenase-2." (PMID 39145770, 2024). "Besides, TNFα coordinated with IFNγ to promote MUC16 (CA125) expression in breast and ovarian cancer via the NF-κB signaling axis." (PMID 38166970, 2024). "In addition, using TNF-α, macrophages significantly increase the expression of the signaling proteins PI3K and Akt to promote migration and invasion abilities in ovarian cancer cell lines in vitro." (PMID 39003350, 2024). "In this paper we investigated whether TNF and other NF-κB activating factors affect the secretion of HE4 in ovarian cancer." (PMID 39621651, 2024). "Previously, an inhibitory role of PI3 in cisplatin-induced apoptosis has been reported in ovarian cancer cells, whereas SLPI inhibited TNFα-induced apoptosis in lymphoma-derived U937 cells; however, a role for apoptosis regulation in brain tumors has not been addressed before." (PMID 37158962, 2023). "Our results demonstrate that Lv-PD1-γδ T cells can generate functional anti-PD-1 antibodies to block the PD-1/PD-L1 inhibitory pathway, resulting in enhanced cytotoxicity and improved therapeutic efficacy in ovarian cancer by secreting high levels of IFN-γ, TNF-α, and granzyme A/B." (PMID 37857598, 2023). "In rat models of ovarian cancer, DEX treatment could effectively decrease the plasma concentration of TNF-α and enhance the immunity through various signaling pathways, which eventually inhibited tumor growth, invasion, and migration." (PMID 36765695, 2023). "The serum IL‐6, TNF‐α, and IFN‐γ levels were closely related to the recurrence of ovarian cancer." (PMID 37904699, 2023). "The LGALS3 inhibitor GB0139 has shown promise in acute lung injury where its mechanism of action involves reducing IL-6, TNF-α, and MIP-1α69, and thus may also prove efficacious in ovarian cancer where TNF-α plays a role in EMT initiation and maintenance." (PMID 38086828, 2023). "To test whether γ‐secretase also controls downstream signaling of Fn14, we used the ovarian cancer SKOV‐3 cell line, which secretes TNF as a result of TWEAK‐stimulated Fn14 signaling in an NFκB‐dependent manner." (PMID 36069059, 2022). "Additionally, Claudin-4 positive human ovarian carcinoma cells experienced a 6.7-fold elevation in toxicity when treated with a fusion of recombinant c-CPE and tumor necrosis factor (TNF) than with TNF alone." (PMID 36077843, 2022). "For the following genes, we found no significant changes in expression in fibroblasts after treatment with exosomes from ovarian cancer cells: HTATIP2 (HIV-1 Tat interactive protein 2, 30 kDa), IL1B, TGFB1 and TNFSF10 (TRAIL, Tumor necrosis factor (ligand) superfamily, member 10)." (PMID 36012171, 2022). "In ovarian cancer cell lines HO8910 and SKOV3, it was demonstrated that TAMs or cytokines released from them, like IFN-γ, TNFα, IL-10, and IL-6, are responsible for the upregulation of PD-L1 expression in the surface of these cells, but no modification in its mRNA was observed." (PMID 33540543, 2021). "KEGG enrichment analysis showed that knockdown of EGFL6 could affect MAPK signaling pathway, TNF, ECM, and Jak-STAT signaling pathways in ovarian cancer cells." (PMID 32983976, 2020).
ovarian carcinoma (continued). "TNF-α and TNFR have been shown to be key positive regulators of the extrinsic apoptosis pathway through the inhibition of the activation of caspases in human ovarian cancer cells." (PMID 32020859, 2020). "Similarly, in breast and ovarian cancers, TA-pDCs show a decreased IFN-α secretion upon TLR7/9 stimulation, but different soluble factors are involved, such as TNF-α and TGF-β." (PMID 32054102, 2020). "Therefore, it is expected that targeting TNF-α/TNFR signaling and downstream NF-κB molecules activation through CME should improve ovarian cancer cell sensitivity to platinum based chemotherapy." (PMID 32020859, 2020). "TNF, ESR1, MUC1 are HOUP genes, suggesting a potential role in ovarian cancer progression." (PMID 32192517, 2020). "Similar results were achieved in other two studies, in which ALT-803 was found to enhance the function of NK cells against several ovarian cancer cell lines, multiple myeloma, and leukemia target cells with significant increases of CD107a, IFN-γ, and TNF-α expression." (PMID 30601063, 2019). "Unlike other reports that demonstrate such binding following stimulation with TNF-α, e.g. in ovarian-carcinoma cells, we did not observe it in fibroblasts, either at baseline or after stimulation (data not shown)." (PMID 30125263, 2018). "Moreover, IAPs are frequently dysregulated in ovarian cancer and have been described as major regulators of the major regulators of TNF-α expression (TNF-α being a highly elevated cytokine in this cancer)." (PMID 30552344, 2018). "Previously, we demonstrated that EGF or TNF could induce the expression of proinflammatory chemokines such as CXCL1, 2, 3 and 8 in ovarian cancer cells via NF-κB, Akt and Erk signaling pathways." (PMID 30034618, 2018). "There appears to be a backfeed interaction between inflammatory mediators and CD44 expression as, tumor necrosis factor-alpha (TNF-alpha), a major inflammatory cytokine, abundant in the ovarian cancer microenvironment was found to differentially modulate CD44 expression in ovarian cancer cells." (PMID 25926834, 2015). "To further analyze the mechanisms of hUCMSCs- LV-IL-21 therapy for ovarian cancer in mice, we designed an experiment to find out whether the serum cytokines of IL-21, IFN-γ, and TNF-α were changed in the mice treated with hUCMSCs-LV-IL-21." (PMID 24444073, 2014). "Following co-culture with ovarian cancer cells, macrophages develop a cell-surface phenotype similar to TAMs isolated from human ovarian tumors and a significant increase in genes such as CCL2, CCL22, TNFα, TGFβ1, and VEGF." (PMID 24936477, 2014). "Also those ovarian cancer cells with a high endogenous expression of TNF, expressed higher levels of CXCR4 than cells with a low TNF expression." (PMID 23800251, 2013). "Also, our previous studies have reported that TNF primarily induces CXCR2 ligands (CXCL1-3 and CXCL8) in ovarian cancer cells." (PMID 24376747, 2013). "High levels of expression of TNF-α have been observed in ovarian carcinoma, particularly of the high grade serous type, and an anti-TNF-α antibody, infliximab (RemicadeTM), has been investigated for its efficacy against ovarian cancer." (PMID 22792380, 2012). "The lack of induction of CCL28 by TNF in these ovarian cancer cells is in contrast to earlier report that TNF and IL-1 increase expression of CCL28 in human keratinocyte cells and colon epithelium." (PMID 23300534, 2012). "The cytokines, including IL-4 (p = 0.017) and TNF-α (p = 0.046), significantly decreased while others such as TGF-β (p = 0.013), IL-6 (p = 0.016), and IL-10 (p = 0.018) were elevated in ascites of ovarian cancer patients, when the disease progressed to advanced stages." (PMID 23082146, 2012). "We previously reported in vitro characterization of a fusion protein, CPE290-319-TNF, and demonstrated that the C-terminal 30 amino acids (amino acids 290-319) of CPE could effectively target TNF to ovarian cancer cells expressing claudin-3 and claudin-4." (PMID 21303546, 2011).
ovarian carcinoma (continued). "Additionally, TNF-α was reported to induce the secretion of MIF from dendritic cells and ovarian cancer cells." (PMID 21152395, 2010). "While its activation in TAMs can reprogram them toward an anti-tumor M1 phenotype, its activation in ovarian cancer cells—via CXCL1, MIP-1β, MCP-1, TNF-α, and RANTES, or other secreted factors might be involved in driving metastasis, immune suppression, and therapy resistance." (PMID 40330466, 2025). "Additionally, studies show that inflammatory cytokines TNFα and IFNγ can stimulate MUC16 expression in breast cancer, endometrial cancer, and ovarian cancer cells via NFκB, and in these cancer tissues, increased MUC16 expression is associated with elevated cytokine levels." (PMID 38361923, 2024). "EOC patients showed higher levels of proinflammatory cytokines (IL-6, TNF-α, and IL-12), regulatory cytokines (IL-10), and chemokines (CXCL-9 and CXCL-10), which corroborated this environmental proinflammatory/regulatory mechanism for the development of ovarian cancer." (PMID 38141599, 2023). "While SHetA2 caused only moderate and no cleavage of caspase eight in lung and ovarian cancer cells, respectively, it sensitized these cancer cells to caspase eight cleavage and apoptosis by death receptor ligands, tumor necrosis factor α (TNFα) and TNF-related apoptosis inducing ligand (TRAIL)." (PMID 35281109, 2022). "RGS10, the most highly expressed protein in peripheral macrophages, inhibits the expression of cyclooxygenase-2 and tumor necrosis factor α (TNFα) through a G protein non-dependent mechanism to regulate inflammatory signaling in microglia and ovarian cancer cells." (PMID 36120550, 2022). "In vitro experiments performed in cervical and ovarian carcinoma cells suggested that TNF-α can enhance topo-II inhibitor–mediated cancer cytotoxicity, Also, increased sensitivity of the type II topoisomerases inhibitor was notwithstanding of the TNF-α resistances." (PMID 35814435, 2022). "Consequently, we will determine the mechanisms of action involved in ovarian cancer tumor growth, we will measure levels of anandamide and 2-arachidonoyl glycerol as well as protein levels of CB1, CB2, ERα, ERβ, GPER, TNFα, IL-1β and IL-6 in ovarian and tumor tissues." (PMID 35242036, 2022). "Among these, δ-Cadinene showed promising apoptotic activity through the growth retardation of ovarian cancer (OVCAR-3) cells via caspase-dependent apoptosis and cell-cycle arrest, and the di-n-octyl phthalate showed antitumor activity via the inhibition of tumor-necrosis-factor production." (PMID 36296555, 2022). "ST6GAL1 exerted a similar effect on tumor necrosis factor (TNF)-induced cell death by sialylation of the TNF receptor 1 (TNFR1), which inhibits its internalization, preventing the induction of apoptosis and promoting cell survival in pancreatic and ovarian cancer cells." (PMID 33921986, 2021). "In summary, our results demonstrate that C. militaris triggers TNF-α/TNFR1-mediated apoptosis by suppressing the NF-κB signaling pathway and promotes the cleavage of caspase-3 and caspase-9 through the induction of the extrinsic apoptotic pathway in ovarian cancer cells." (PMID 32020859, 2020). "Serum concentration of IL-10 in ovarian cancer patients correlated positively with peritoneal fluid concentration of this cytokine and serum level of TNF-alpha; moreover, women with ovarian malignancies showed a positive correlation between serum TNF-alpha an IL-10 in peritoneal fluid." (PMID 28376925, 2017). "Therefore, high levels of TNF and frequent overexpression of EGFR observed in ovarian cancer could provide the fundamental basis for the higher expression of CCL20 in SKCXCR2-derived tumor tissues." (PMID 27723802, 2016). "It remains to be determined whether TNFα and IL6 increase STS activity in ovarian cancer cells." (PMID 25817828, 2015).
ovarian carcinoma (continued). "In effect, TNFα can amplify the CXCL12 signal, and therefore neutralising TNFα, neutralising CXCL12, antagonising CXCR4 or inhibiting NF-κB may be an effective therapy for ovarian cancer." (PMID 22415233, 2012). "Interestingly, TNF is generally recognized to inhibit or kill tumor cells through multiple links, TNF receptors (TNFR), especially TNFR1, have been found to be upregulated in a variety of tumors, such as ovarian cancer, renal clear cell carcinoma and acute myeloid leukemia." (PMID 36506314, 2022). "Importantly, these CE7R+ TCM cells were capable of secreting high levels of IFN-γ and TNF-α, and exhibited robust and specific in vitro lytic activity against L1-CAM/CE7+ ovarian tumor cells—both established lines and primary tumor cells derived from the malignant ascites of ovarian cancer patients." (PMID 26761817, 2016). "Human ovarian cancer cell lines were stimulated with or without PARP inhibitors olaparib and niraparib in the presence or absence of TNF-α." (PMID 39862711, 2025). "TNFα (25 ng/ml), which has been previously reported to stimulate MUC16 expression in breast and ovarian cancer cells, failed to increase MUC16 protein expression in HPMCs." (PMID 31039761, 2019). "In a mouse xenograft model of non-high grade ovarian cancer (IGROV-1 cells), CX-4945 treatment prevented tumor growth, decreased vascular area and proliferative index, and prevented mRNA expression of TNF, IL-6, and VEGF." (PMID 28134850, 2017). "A recent study exploring the impact of several different media formulations on cell therapy products found that exposure to ascites from ovarian cancer patients reduced IFN-y and tumor necrosis factor alpha (TNF-a) production by T cells regardless of expansion condition." (PMID 36479131, 2022). "To further examine the impact of T-DM1 on cytokine-mediated bystander killing in our panel of breast and ovarian cancer cell lines, we treated JIMT1, SKOV3, T47D and MCF7 cells with T-DM1, colchicine, trastuzumab or vehicle, in the presence or absence of 100 μg/ml TNFα." (PMID 32444806, 2020). "Interestingly, although the combination of TNFα and IFNγ could induce the production of CCL5 in ovarian cancer ascites cells or macrophages, their joint blockade did not abrogate induction of CCL5 in co-cultures of activated CD8+ T cells with ascites cells or myeloid cells." (PMID 41142824, 2025).
schizophrenia (292 papers, 2005 to 2026). A major psychotic disorder characterized by abnormalities in the perception or expression of reality. "The inflammatory biomarkers most frequently associated with CT are CRP, IL-1β, IL-6, and TNF-α, parameters which have also been found to be elevated in schizophrenia." (PMID 41049865, 2025). "Both ASD and schizophrenia have been associated with elevated levels of pro-inflammatory cytokines such as IL-6, IL-1β, and TNF-α, as well as microglial activation and altered blood–brain barrier permeability." (PMID 40724876, 2025). "This genomic region contains variants that influence both infection susceptibility and schizophrenia risk, including the TNF-α -G308A polymorphism associated with neuroanatomical changes and earlier disease onset." (PMID 40806558, 2025). "Increased concentrations of IL-1β, IL-6, IL-10, IL-17, sIL-2R, and IL-33, but also decreased concentrations of TNF-α, were similarly associated with more severe positive symptoms of schizophrenia." (PMID 40364201, 2025). "Using Mendelian Randomization analysis, we found nine inflammatory proteins, including IL-1A and TNF-α, that contribute to the genetic susceptibility of schizophrenia." (PMID 39544374, 2024). "The aim of this study was to assess the clinical significance of the plasma levels of TNF-α and sTNF-α R1 in first episode patients with schizophrenia (FEPS), and their potential association with agitation." (PMID 38956509, 2024). "Not only was an association between elevated TNF-α serum levels and schizophrenia demonstrated, but a positive correlation between schizophrenic symptoms and TNF-α was found." (PMID 38731913, 2024). "In patients with schizophrenia, TNF-α has been associated with various domains of cognitive function." (PMID 38429778, 2024). "In conclusion, altered peripheral TNF-α levels are associated with the psychopathology, and in particular with agitation in patients with schizophrenia." (PMID 38956509, 2024). "Schizophrenia is associated with elevated levels of IL-6, IL-8, and TNF-α and reductions in the anti-inflammatory IL-10." (PMID 38673018, 2024). "Despite the small sample size (N = 27/50 case/controls), it was reported that elevated maternal serum TNF-α during pregnancy had an association with the risk (8.5 odds ratio (OR)) of schizophrenia later in their offspring." (PMID 37627253, 2023). "Because NFkB and PPARs are dysregulated in schizophrenia and are associated with higher levels of neuroinflammation, the agonist of PPARs can reduce inflammatory processes, reducing TNF-α and IL-6 levels." (PMID 37371435, 2023). "A recent meta-analysis revealed an association of schizophrenia risk with genetic variants in the promoter region of TNFα." (PMID 37032951, 2023). "Particularly at the onset of schizophrenia and during the recurrence of psychotic episodes, blood levels of proinflammatory cytokines such as IL-1β, IL-6, and TNF-α tend to increase, and levels of IL-6 are associated with poor schizophrenia prognosis." (PMID 37371435, 2023). "It has previously been shown that there is a positive association between IL-1β, IL-6, and TNF-α and prolactin levels in patients with schizophrenia." (PMID 35958655, 2022). "In any situation where JNK activity is elevated (as for example in genetic predisposition to schizophrenia, this induction of TNFα will be even further increased." (PMID 34297254, 2022). "Brain TNF-α is the most promising pharmacological target for the treatment of neuroinflammation that is known to be associated with schizophrenia." (PMID 34763685, 2021). "In particular, we have determined to the best of our knowledge that there is no current study examining sex differences in the association between TNF-α, the OxS system, and their interrelationship with clinical symptoms in patients with schizophrenia." (PMID 34526062, 2021). "Other GWA studies have not found the association between (1031 T/C and 308 G/A) promoter polymorphisms in the TNF-α gene and schizophrenia risk." (PMID 33746786, 2021).